PDCD10 (programmed cell death 10)
Diseases named in the same sentence as PDCD10 in open-access papers (continued):
Sharing a sentence is not in itself a finding about the gene and the disease.
tumor (continued). "However, the updated data seem to indicate that PDCD10 has a dual role (either pro- or anti-tumor effects) in various cancer types, depending on cell/tissue specificity with different cellular interactors." (PMID 36497468, 2022). "Thus, we assumed that CXCR2 is involved in aggressive behaviors of tumor cells mediated by PDCD10 in PAs." (PMID 35963638, 2022). "Additionally, the knockdown of PDCD10 in tumor cells also facilitated angiogenesis in a mice GBM xenograft model." (PMID 36497468, 2022). "However, the updated data tend to indicate that PDCD10 plays a dual role (either pro- or anti-tumor effects) in various cancers, depending on cell/tissue specificity with different cellular interactors." (PMID 36497468, 2022). "Interestingly, loss of PDCD10 in endothelial cells was also found to promote GBM growth 103], suggesting a bidirectional dependency between tumor cells and endothelial cells." (PMID 36497468, 2022). "Studies have shown that altering the activity or the expression level of STK25 and regulating cell proliferation/apoptosis/polarity by STK25/GM130/PDCD10 may provide new directions for tumor therapy." (PMID 35265128, 2022). "Besides, the Ki-67 staining, a proliferation indicator, was also decreased in PDCD10-silencing tumor samples according to IHC results." (PMID 35963638, 2022). "PDCD10 expression was higher in several tumor tissues than in normal tissues, indicating that PDCD10 may act as an oncogene in these tumors, which is consistent with previous findings." (PMID 36276268, 2022). "As an adaptor protein, PDCD10 seems to have a dual role (either pro- or anti-tumor effects) in various cancer types, which may depend on cell/tissue specificity with different cellular interactors." (PMID 36497468, 2022). "The programmed cell death molecule 10 (PDCD10), another PRF, is highly evolutionarily conserved and encodes for a gene that plays a role in the regulation of angiogenesis, proliferation, apoptosis, and migration of tumor cells." (PMID 35706452, 2022). "However, we compared expression profiles between tumor grades and found that SNX15, ATP2A1, PDCD10, BET1, and HMGA2 expressions were significantly (all p < 0.05) associated with tumor stages." (PMID 34831096, 2021). "The number of infiltrated microglia/macrophages in tumor core was larger in oxPdcd10-group than that in control group (p<0.001), and a positive correlation was revealed between PDCD10 expression and infiltration of microglia/macrophages, which was consistent with our findings in GBM patients." (PMID 34108959, 2021). "Considering the high PP2Ac activity in HCC cells with high PDCD10 expression, we asked whether LB-100 could reduce the tumour-promoting function of PDCD10." (PMID 34521817, 2021). "In summary, loss of PDCD10 activates GBM cells and promotes tumor growth via triggering EphB4." (PMID 32850441, 2020). "The functional study demonstrated that upon NVP treatment, the inhibition of EphB4 kinase activity can inhibit the aggressive behavior in shPDCD10 GBM cells, as well as hinder rapid tumor formation and proliferation, thereby leading to a reduction of the tumor mass in PDCD10 knockdown tumor." (PMID 32850441, 2020). "The NVP treatment completely reversed the upregulation of p-EphB4 in xenograft tumors of the PDCD10-knockdown mice Consequently, the tumor progression was significantly faster in the shPDCD10-mice than that in the controls as inspected from day 7 to day 21 after implantation." (PMID 32850441, 2020). "Restoration of PDCD10 expression reversed the inhibition of tumor metastasis by miR-222-3p." (PMID 32483426, 2020). "In this study, we speculate that EphB4 is the target of PDCD10 in GBM cells and that interfering EphB4 signaling could rescue the phenotype of PDCD10-deficient GBM cells and suppress tumor growth in a mouse model of GBM." (PMID 32850441, 2020).
tumor (continued). "PDCD10 overexpression or administration of a ROCK inhibitor reversed TRIM59 loss-induced contractile phenotypes, thereby accelerating cell migration, invasion, and tumor formation." (PMID 30408026, 2018). "The binding miRNA miR-103a can suppress tumor cell proliferation by targeting PDCD10 in PCa, suggesting that circBAGE2 may have a close relevance with the progression of PCa." (PMID 30416748, 2018). "KO of either TRIM59 or PDCD10 suppressed MCF7 xenograft tumor growth to a similar extent." (PMID 30408026, 2018). "The absence of PDCD10 immunoreactivity in proliferating tumor and its concomitant co-localization with apoptotic marker in pseudopalisade tumor cells may suggest the involvement of PDCD10 in the progression of GBM." (PMID 26490252, 2015). "Moreover, gene chip analysis indicated the involvement of PDCD10 in tumor signaling and in resistance to chemotherapy-triggered apoptosis." (PMID 26490252, 2015). "In particular CASP2, JNK2, PDCD10, and ST13 have been associated with mitochondrial permeabilization and with the induction of the apoptotic process, while SPARC overexpression seems to play a tumor suppressor function in some low expressing SPARC AMLs." (PMID 24148231, 2013). "However, PDCD10 seems to have a dual role (either pro- or anti-tumor effects) in various cancer types, which may depend on cell/tissue specificity with different cellular interactors." (PMID 36497468, 2022). "Thus, it can be speculated that PDCD10 might contribute to tumor progression in PAs by inducing EMT." (PMID 35963638, 2022). "Finally, the pro-oncogenic effect of PDCD10 was confirmed by in vivo tumor grafting." (PMID 35963638, 2022). "We conducted a survival analysis using the GEPIA2 database to investigate whether or not PDCD10 expression is associated with a better or worse outcome for patients with various tumor types." (PMID 36276268, 2022). "Targeting PP2Ac could abolish the tumour-promoting role of PDCD10 in HCC." (PMID 34521817, 2021). "We hypothesized that loss of PDCD10 activates GBM cells and tumor progression via EphB4." (PMID 32850441, 2020). "However, the role of PDCD10 in tumor cells remains elusive and appears context dependent." (PMID 32850441, 2020). "Inhibition of known tumour-suppressors PTEN and PDCD10 is expected to increase cell proliferation, thus these genes were not included in our further analysis." (PMID 37996617, 2024). "In sum, CXCL2-CXCR2 signalling stimulated by PDCD10 appears to be a key mechanism in the crosstalk between GBM cells and microglia/macrophages that promotes tumour progression." (PMID 36555253, 2022). "High PDCD10 expression promotes HCC cell proliferation, migration, and invasion in vitro and tumour growth, metastasis in vivo." (PMID 34521817, 2021). "As a result, we demonstrate overexpression of PDCD10 in GBM recruits and activates microglia/macrophages, which in turn promotes tumor progression." (PMID 34108959, 2021). "Our study demonstrates that overexpression of PDCD10 in GBM recruits and activates microglia/macrophages, which in turn promotes tumor progression." (PMID 34108959, 2021). "The IHC staining of the metastatic tumor on the stomach tissues of mice detected significantly higher expression of PDCD10 protein in the LV-miR-ctrl and OE-PDCD10 co-transfected groups, and this expression could be reversed in the LV-miR-222-3p and PDCD10 co-transfected group." (PMID 32483426, 2020). "Taken together, these results suggested that miR-222-3p acted as a tumor-suppressor gene to inhibit HO 8910 PM and SKOV3 cell migration by directly suppressing PDCD10 expression." (PMID 32483426, 2020). "Our study found that miR-222-3p/PDCD10 had a tumor-suppressive role by decreasing PDCD10 expression, which in turn inhibited EOC cell migration in vitro and tumor metastasis in vivo." (PMID 32483426, 2020).
tumor (continued). "Herein, we found that miR-222-3p acted as a tumor-suppressor to inhibit EOC cell migration and tumor metastasis by targeting PDCD10, revealing the significance of miR-222-3p and PDCD10 in EOC." (PMID 32483426, 2020). "PDCD10 (CCM3) is a member of the CCM family, which includes CCM1 and CCM2 reported to be involved in tumor metastasis, and in many cardiovascular diseases." (PMID 32483426, 2020). "Moreover, as SERPINI1 and SERPINI2 were both reported to be down-regulated during tumor development, it is rational to doubt that the expression of PDCD10, which is located in between the two SERPINI genes at chromosome 3q26, may also be altered in some tumors." (PMID 17212813, 2007). "An immunohistochemistry study revealed that PDCD10 was absent in the majority of tumor cells and in tumor endothelial cells, which was correlated inversely to tumor cell proliferation and hyperangiogenesis." (PMID 39273014, 2024). "The PDCD10 knockdown cell-derived GSCs may, thus, serve as the origin of TMZ-resistant and rapidly regrowing cells, accounting for tumor recurrence." (PMID 39273014, 2024). "Therefore, we constructed PDCD10 knockdown cell lines with U2OS and MG63 cells and conducted a series of tumor cell function tests." (PMID 35848121, 2023). "Regardless of the dual role of PDCD10 in oncogenesis, developing drugs that target PDCD10 in specific tumor types is still a promising perspective for cancer therapy." (PMID 36497468, 2022). "In addition, the expression levels of Ki-67, which represents a level of tumor proliferation, together with CXCR2 were decreased in the PDCD10-shRNA group." (PMID 35963638, 2022). "Suggestively, our results indicated that SNX15, ATP2A1, PDCD10, BET1, and HMGA2 could serve as a biomarker signature of tumor progression and metastasis in CHOL patients." (PMID 34831096, 2021). "Indeed, functional experiments showed that PDCD10 promotes HCC cell proliferation, migration and invasion in vitro and tumour growth and metastasis in vivo, which confirmed the oncogenic role of PDCD10 in HCC metastatic progression." (PMID 34521817, 2021). "Furthermore, We observed direct binding of miR-222-3p to the 3'-UTR of PDCD10 and inhibition of PDCD10 translation, which, in turn, inhibited EOC cell migration in vitro and repressed EOC xenografted tumor metastasis in vivo." (PMID 32483426, 2020). "Moreover, knockdown of either EC-originated or TC-originated PDCD10 activated GBM cells and promoted tumor growth via stimulating the release of a group of growth factors and angiogenic factors." (PMID 32850441, 2020). "Our data revealed that miR-222-3p could target PDCD10 and inhibit its translation thereby impeding EOC cell migration in vitro and repressing EOC xenografted tumor metastasis in vivo." (PMID 32483426, 2020). "Our data revealed that miR-222-3p could target PDCD10 and lead to inhibition of PDCD10 translation, which inhibited EOC cell migration in vitro and repressed EOC xenografted tumor metastasis in vivo." (PMID 32483426, 2020). "Also, the miR-222-3p/PDCD10 regulatory axis decreased the migration of EOC cells and tumor metastasis by enhancing the expression of cell adhesion molecules, such as E-cad, and reducing the cellular levels of β-catenin." (PMID 32483426, 2020). "More interestingly, we observed the absence of PDCD10 immunoreactivity in the majority of endothelia of tumor vessels and in tumor cells." (PMID 32850441, 2020). "Furthermore, NVP treatment significantly suppressed PDCD10-knockdown mediated aggressive GBM cell phenotype in vitro and extensive tumor cell proliferation, the tumor neo-angiogenesis, and a quick progression of tumor formation in vivo." (PMID 32850441, 2020). "Therefore, it is comprehensive that the knockdown of endothelial PDCD10 activates GBM cells and promotes tumor growth via stimulating multiple growth factors and angiogenic factors." (PMID 32850441, 2020).
tumor (continued). "Loss of PDCD10 decreased the stability of VEGFR2 protein, hinting that TRIM59 might stabilize VEGFR2 protein through PDCD10 to augment VEGF signaling and tumor angiogenesis." (PMID 30408026, 2018). "In contrast, nearly all tumor cells and microvessel endothelial cells in the infiltrating zone were absent of PDCD10 immuno-signal (green) but showed strong PCNA immunoreactivity (red) and appeared negative for caspase 3 staining." (PMID 26490252, 2015). "PDCD10 immunoreactivity was absent in proliferating tumor cells, endothelial cells and GFAP-positive cells, but exclusively present in the hypoxic pseudopalisading cells which underwent apoptosis." (PMID 26490252, 2015). "Moreover, Pdcd10-upregulated GL261 cells promoted GAMs recruitment and tumor growth in vivo." (PMID 34108959, 2021). "PDCD10 expression was negatively correlated (r = −0.33~−0.43, p < 0.05) with tumor infiltration by MAIT, NK cells, and monocytes, and positively correlated (r = 0.29~−0.51, p < 0.05) with tumor infiltration by B cells, CD4_T cells, DCs, iTregs, nTregs, and Tr1s." (PMID 34831096, 2021). "Moreover, a PP2Ac inhibitor (LB100) could restrict tumour growth and metastasis of HCC with high PDCD10 expression." (PMID 34521817, 2021). "Based on these findings together with the previous observation that PDCD10 was absent not only in the majority of ECs but also in TCs of the tumor tissue resected from GBM patients, we recently extended our research to study the role of TC-originated PDCD10 in GBM." (PMID 32850441, 2020). "In our previous study, we could demonstrate that PDCD10 was often absent in endothelial cells (ECs) of tumor vessels as well as in GBM cells (TCs) of human GBM; PDCD10 expression was associated with a higher microvessel density in GBM." (PMID 32850441, 2020). "Immunohistochemistry (IHC) also revealed that PDCD10 staining was strongest in HCC tumour tissue with MVI, followed by tumour without MVI, and ANLT showed the lowest PDCD10 expression." (PMID 34521817, 2021). "The present study identified the absence of PDCD10 expression in tumor cells and endothelial cells in the infiltration area and in the necrotic center of GBM but an exclusive expression of PDCD10 in some pseudopalisading cells, indicating a distinct regional expression manner of PDCD10." (PMID 26490252, 2015).
cancer (32 papers, 2007 to 2026). A tumor composed of atypical neoplastic, often pleomorphic cells that invade other tissues. "By targeting PDCD10, miR-30a-5p thus enhanced cancer-associated angiogenesis, induced vascular permeability and boosted the subsequent metastasis." (PMID 37781039, 2023). "Coincident with that, the current study clarified that PDCD10 in endothelial cells impaired cancer-associated neovascularization and improved vascular permeability." (PMID 37781039, 2023). "We investigated CAF expression markers in various cancer types to elucidate the mechanisms underlying the link between PDCD10 expression and CAF." (PMID 36276268, 2022). "Our data showed that PDCD10 expression was highly linked with the immunological subtypes of many cancer types, including PC, OV, CRC, and STAD, suggesting that this protein plays a crucial role in cancer immunotherapy." (PMID 36276268, 2022). "PDCD10 is also involved in angiogenesis and vascular reconstruction and closely associated with the prognosis of cancer patients." (PMID 26400441, 2015). "PDCD10 overexpression is linked to certain molecular subtypes of human cancer." (PMID 36276268, 2022). "PDCD10 is also associated with maintaining the stemness of cancer stem cells." (PMID 36497468, 2022). "The underlying mechanism by which PDCD10 regulates the EMT process in cancers may be mediated by the nuclear translocation of YAP and the downregulation of Rho/ROCK signaling." (PMID 36497468, 2022). "Moreover, over the past few decades, accumulating evidence has demonstrated that the aberrant expression or mutation of PDCD10 is extremely common in various pathological processes, especially in cancers." (PMID 36497468, 2022). "In this review, we provided an overview of the structure, interactors and regulators of PDCD10, and summarized the molecular functions of PDCD10 in cancers." (PMID 36497468, 2022). "We carefully examined the expression and prognostic significance of PDCD10 in various cancer types to understand its function in cancer development." (PMID 36276268, 2022). "Using the TIMER 2.0 database, we compared the expression of PDCD10 with those of other TME components in many cancer types to understand the function of PDCD10 in the TME." (PMID 36276268, 2022). "In this review, we aimed to summarize the knowledge of the dual role of PDCD10 in cancers with a special focus on its cellular function and potential molecular mechanism." (PMID 36497468, 2022). "The contradictory effect of PDCD10 on YAP activation suggests that the function of PDCD10 depends on cell/tissue specificity with different cellular interactors in cancers." (PMID 36497468, 2022). "The results of our investigation demonstrate that PDCD10 has an oncogenic function in many cancer types." (PMID 36276268, 2022). "The GCKIII kinases regulated by PDCD10 have recently been demonstrated to determine the mode of cancer cell migration and metastasis." (PMID 36497468, 2022). "Targeting these regulators of PDCD10 also seems to be an efficient strategy for the treatment of cancers." (PMID 36497468, 2022). "A growing body of evidence reveals the oncogenic functions of MTDH and PDCD10 in regulating cancer progression." (PMID 36071474, 2022). "With these efforts, we hoped to provide new insight into the future development and application of PDCD10 as a clinical therapeutic target in cancers." (PMID 36497468, 2022). "In line with our observations, oncogenic roles of PDCD10 were reported in various cancers including breast, bladder, prostate, ovarian, and several other cancers." (PMID 34831096, 2021). "Previous reports revealed that PDCD10 in malignant tumors exerted dual functions through a cell-type dependent manner." (PMID 34108959, 2021). "We also found that overexpression of PDCD10 increased cancer metastasis by down-regulating CDH1, enhancing VIM expression, and inducing EMT." (PMID 32483426, 2020).